IL10 (interleukin 10)
Diseases named in the same sentence as IL10 in open-access papers (continued):
Sharing a sentence is not in itself a finding about the gene and the disease.
infection (continued). "The use of the RhCMV model was essential since, in contrast to murine CMV, RhCMV encodes a viral IL-10 (RhCMVIL-10) and displays similar infection routes, seroconversion rates, and sheds virus in urine and saliva as observed for HCMV." (PMID 22132227, 2011). "Strikingly, infection with C5507 Vi+ was also associated with a significant increase in the percentage and total number of cells producing the anti-inflammatory cytokine IL-10 when compared to both stimulated naïve and SGB1 Vi− infected cells." (PMID 21829346, 2011). "The cytokine profile in reactivating Tm-TNF mice reported here contrasts to that observed in de novo infected Tm-TNF mice with respect to pulmonary IFNγ AND IL-10 concentrations during late stage infection despite similar observed susceptible phenotypes." (PMID 22132068, 2011). "A mutation in fetal Il-10 (-1082A) was associated with infection-related preterm birth as were other gene polymorphisms in mother and fetus." (PMID 22114461, 2011). "In contrast, Th2 responses, which are characterized by the production of IL-4, IL-13 and IL-10, result in susceptibility to infection." (PMID 21390155, 2011). "On the other hand, B-cells lacking Myd88 or TLR2 -in contrast to wild type B-cells- were incapable of preventing the characteristic infection-associated immunopathology of Myd88-/- or IL-10-/- strains when adoptively co-transferred with Tr1 cells." (PMID 22044597, 2011). "Hosts who produce IFN-γ/IL-4/IL-5 in association with IL-10 present high levels of infection, proposing that the regulatory component is strongest to define the severity of pathology." (PMID 20544012, 2010). "The dichotomy between the LGT and UGT was maintained during infection by IL-10 because in IL-10-deficient mice the distinction between the two compartments was completely lost and a dramatic shift to the predominance of Th1 cells in the LGT occurred." (PMID 21079691, 2010). "Role of IL-10 in parasite persistence and establishing latency associated with natural infection has been demonstrated using knockout mice." (PMID 20404924, 2010). "On the contrary, IL-10 deficient mice infected with the West Nile virus are better protected from the infection and enjoy a better survival than control, WNV infected mice." (PMID 20886083, 2010). "Screenings for possible insert specific effects examined IL-10, IL-12 and IL-18 which have been implicated as protective during infection by intracellular pathogens." (PMID 20642814, 2010). "In a previous report on a longitudinal study of genital CT infection, in vitro IL-10 production by PBMCs stimulated with recombinant chlamydial antigens was the greatest risk factor for recurrent infections." (PMID 19397832, 2009). "In an early phase of the infection, IL-10 attenuates mechanisms that cause activation of adaptive immune effector cells." (PMID 19412539, 2009). "Studies with Candida albicans have shown that TLR2−/− mice are more resistant to this infection, a fact associated with the decreased release of anti-inflammatory cytokines, such as IL-10." (PMID 19229338, 2009). "Functions most strongly associated with virulent strain infection included cytokine–cytokine receptor interactions and a number of immune signaling pathways, such as interleukin (IL)-6, IL-10 and nuclear factor κB." (PMID 19845042, 2009). "In the Upper-East region of Ghana where infection has remained the leading cause of death, we studied the effect on survival of genetic variations at the IL10 gene locus that have been associated with chronic diseases." (PMID 19907653, 2009). "The positive association of IL-10 and infection intensity has previously been reported in S. mansoni-exposed Brazilians." (PMID 18045464, 2007). "Moreover, IL-10 performs a wide range of functions that reduce tissue damage caused by inflammation or infection." (PMID 41463795, 2025). "However, IL-10 has been associated with inflammation, protracted postpartum infection and damage to uterine local resistance." (PMID 40005882, 2025).
infection (continued). "In conclusion, when infected directly at nasal mucosa, L. amazonensis parasites are more proliferative and lead to an increased inflammatory response compared to ear dermis infection, which can be associated with the IL-10 impairment related to the immunopathology of MCL." (PMID 40831564, 2025). "The decrease in anti-inflammatory cytokines, such as IL-4 and IL-10, may be associated with better regulation of the immune system, resulting in greater control of infection and a balanced inflammatory response." (PMID 40367013, 2025). "IFN-γ expression is associated with resolving infection in mammals, since this cytokine induces parasite killing by macrophages following nitric oxide release, as well as causing the direct inhibition of IL-4 and IL-10 production." (PMID 41471158, 2025). "Similarly, IL-10, known for its potent suppressive effects on monocyte differentiation, is associated with increased susceptibility to infection with PRRSV by enhancing the expression of CD163 and CD169 in monocytes." (PMID 41156600, 2025). "On the other hand, IL-10, an anti-inflammatory cytokine, plays a regulatory role in dampening excessive inflammation, but imbalanced IL-10 levels are associated with impaired immune responses and increased susceptibility to infection." (PMID 40142333, 2025). "Importantly, IL-10-deficient DCs pulsed with parasite antigens protect against lethal infection, enhancing Th1 response and antigen-specific T cell expansion." (PMID 41568009, 2025). "Similarly, N. brasiliensis infections reduced allergic responses, particularly when the infection occurred weeks before allergen exposure, with the protective effect linked to IL-10." (PMID 40432048, 2025). "Interestingly, the GA genotype of IL-10-1082 A > G had a significant association with case fatality in influenza A/H1N1pdm09 infections in Indian patients and other viruses." (PMID 38287362, 2024). "Cytokines, pivotal in T helper cells’ function regulation, play a role in this balance, with increased production of Th1-associated cytokines, which are essential for infection control, while Th2-related cytokines, such as IL-10, are linked to susceptibility against L. infantum multiplication." (PMID 38396573, 2024). "Infection with P. berghei caused liver tissue inflammation, which was shown by a significant increase (p < 0.05) in the levels of the pro-inflammatory cytokines IL-10 and IL-1β." (PMID 39726977, 2024). "Furthermore, a polymorphism in the region encoding IL-10 has been associated with increased IL-10 production and susceptibility to infection by L. braziliensis in humans." (PMID 38455048, 2024). "This is in line with prior findings of IL-10 c-aAb being associated with reduced infection risk in Danish blood donors, which we speculate is due to the anti-inflammatory role of IL-10, where c-aAb-mediated inhibition may result in a more active immune system." (PMID 39606243, 2024). "Autocrine IL-10 production plays a critical role in promoting the development of M2 macrophage polarization, which is linked with poor Mtb clearance in later stages of infection." (PMID 38922041, 2024). "Therefore, human gut microbiota-associated IL-10−/− mice were orally subjected to synthetic menthol starting a week before C. jejuni infection and followed up until day 6 post-infection." (PMID 38540710, 2024). "While IL-10 is known to dampen inflammation, the IL-6 is a pleotropic cytokine whose biological functions have also been linked to immunomodulation during the stages of infection resolution." (PMID 38683795, 2024). "Elevated IL-10 in the peripheral blood has also been associated with severe disease, but may be useful later in the infection to suppress the hyper-cytokinemia associated with ARDS." (PMID 39531435, 2024). "Conversely, elevated IFN-γ levels and reduced IL-10 are associated with worsening infection." (PMID 39703398, 2024).
infection (continued). "We find that both resident and recruited γδ T cells are part of this induced wound healing response via production of IL-17A and IL-22, as well as the induction of IL-10 in other cells, and that a deficit in γδ T cells causes a profound increase in tissue pathology following infection." (PMID 38543790, 2024). "This difference of IL-10′s impact on skin and systemic infections may be partly linked to differences in the primary cellular sources of IL-10 in various infection contexts." (PMID 38786139, 2024). "In addition, immunohistochemical analysis showed multi-focal granulomatous hepatitis associated with chlamydial antigen and IL-10 overproduction, indicating compromised ability to control early infection stages." (PMID 39199857, 2024). "This discovery is particularly relevant in context of TB infection, where the elevated levels of IL-10 could alter macrophage susceptibility to lysis by CD8+T cell effectors at the infection site." (PMID 39003443, 2024). "In VL, Th1 cells produce pro-inflammatory cytokines such as IFN-γ and TNF-α, which induce phagocytic activity and control parasitic growth while Th2 cells produce a higher level of IL-4, IL-5, IL-13, and IL-10 that leads to susceptibility towards infection (Refs." (PMID 39587036, 2024). "Whether GC-enhanced local secretion of IL-10 is sufficient to suppress inflammation activation associated with symptomatic infection is unknown." (PMID 39585777, 2024). "Additionally, dysregulation of IL-10 is associated with enhanced immunopathology in response to infection." (PMID 38802892, 2024). "Conversely, the anti-inflammatory response, marked by increased anti-inflammatory cytokines like interleukin-10 (IL-10), may result in immune suppression and an impaired ability to clear the underlying infection." (PMID 38455817, 2024). "Regarding the IL-10 gene polymorphism, we found that the CA and CC genotypes as well as the C allele of the IL-10 (-1082 G>A), rs1800896 polymorphism are associated with high risk of infection: OR 2.0596 (1.1587 - 3.6609), OR 3.5(1.4505 - 8.445), and OR 2.0108 (1.3442 – 3.0081) respectively." (PMID 38544825, 2024). "B-cell derived IL-10, primarily produced by Breg-like cells, plays a crucial role in distorting the immune response towards Th2 cell development and promoting susceptibility to infection with L. major LV39." (PMID 37235324, 2023). "This change in cytokine response, notably the increased expression of IL-10, may skew for a Th2-typed immune response, a hallmark of severe infections." (PMID 37896776, 2023). "It has also been described that the IL-10-producing-Treg subset was increased in severe patients and could be responsible for truncating adaptive immune responses, allowing infection to persist and thus causing over-reliance on innate responses." (PMID 37311004, 2023). "Reduced bacterial burden in the brains of IL-10 KO mice at day 14 post-infection was associated with a significant decrease in G-MDSC infiltrates, a pathologically activated PMN population that inhibits T cell activation, macrophage proinflammatory activity, and PMN bactericidal activity." (PMID 37179295, 2023). "Our results suggest that decreased IL-10 production during GBS infection in TLR2/4-deficient mice reduces the severity of ascending infection and may promote bacterial clearance." (PMID 37747229, 2023). "The authors consider that the beneficial or detrimental roles of IL-10 might depend on whether the major cause of host death is pathogen overload or excessive inflammation during infection." (PMID 36776839, 2023). "The increased production of this chemokine enhances the LPS-induced production of IL-10 and causes increased migration of immune cells to a site with an infectious agent, which may favor a rapid response and resolution of the infection." (PMID 37520439, 2023). "IL10 rs1800871/rs1800872 CC/CC diplotype may predispose Japanese children to ANE by altering IL-10 production in the early phase of infection." (PMID 37600000, 2023).
infection (continued). "However, IL-10 has been shown to be the cause of inflammation, persistent post-partum infection, and damage to uterine local resistance." (PMID 37368756, 2023). "IL-10 has also been associated with the ability of Mycobacterium tuberculosis to evade host immune responses, and consequently, blockade of the IL-10 receptor was noted to alleviate these infections." (PMID 37747229, 2023). "However, higher levels of IL-10 were measured in the lungs of LysM-/- mice upon Klebsiella pneumoniae infection, despite increased susceptibility to infection as compared to WT mice." (PMID 37876927, 2023). "Infection caused only two uniquely upregulated genes, Il10 (IL-10) and Rag2." (PMID 37929965, 2023). "Excessive IL-10 is regarded as a critical biomarker following pathogen infections in fish, where moderately controlled IL-10 expression levels indicate recovery, and overproduction is associated with severe infection." (PMID 37649642, 2023). "We can speculate that fractions, in the infection with pathogenic bacteria, can have altered role in IL-10 regulation." (PMID 36466691, 2022). "In pigs, previous studies described how recombinant porcine IL-10 was able to increase susceptibility to infection with porcine reproductive and respiratory syndrome virus (PRRSV) in either two-day-old monocytes, moMΦ, or monocyte-derived dendritic cells (moDC)." (PMID 35215110, 2022). "The reduced IL-10 levels in TB groups are quite contrary to the reported studies and were associated with greater pathogen clearance; however, loss of immunity was observed during re-infection." (PMID 35911760, 2022). "Therefore, if IL‐10 is expressed at an inopportune time, such as too early during virulent infection, or too late during avirulent infection, it can cause overwhelming infection or severe tissue damage." (PMID 36176597, 2022). "In addition, during the late stages of the infection, IL-27 along with IL-10 is considered to limit tissue damage caused by L. braziliensis." (PMID 35090305, 2022). "Moreover, another group showed that both B6 and BALB/c mutant lineages deficient in IL-10 production presented better control of the infection, associated with an early development of Th1 response." (PMID 36678397, 2022). "Thus, we conclude that psychological stress in old mice prior to infection, increases differentiation of IL-10 secreting T cells, which over time results in loss of control of the infection." (PMID 36189368, 2022). "Interleukin-10 (IL-10) is an anti-inflammatory cytokine that regulates and inhibits the synthesis of pro-inflammatory cytokines, aiding in the natural resolution of infection and minimizing tissue damage caused by inflammation." (PMID 36358281, 2022). "Interestingly, after the Mtb challenge, mice immunized with rBCG-LTAK63 showed an increased production of regulatory-related cytokines (TGF-beta and IL-10) in the lungs, resulting in considerable reduction of the inflammation associated with infection." (PMID 36119106, 2022). "Additionally, Fc deficient mice infected by L. amazonensis were observed to produce less IL-10 and to be less susceptible to infection." (PMID 36579347, 2022). "Moreover, it rapidly reduced the expression of IL-10 in the later stage with the decline of IL-1β, IL-6, TNF-α, and IFN-γ, to prevent the continuously excessive release of IL-10 from causing severe immune suppression and uncontrollable infection." (PMID 35071595, 2022). "Although our studies indicate that psychological stress in old mice increases the loss of control of the infection by increasing differentiation of IL-10 secreting T cells, further studies are needed to elucidate the mechanisms by which psychological stress alters T cell differentiation." (PMID 36189368, 2022). "IL-10-deficient mice also uniformly succumb to infection with the P. yoelii (Py) 17XNL line." (PMID 35631044, 2022).
infection (continued). "As most TLRs recruit general adaptor protein MyD88 to activate NF-κB, infection of MyD88-deficient macrophages, as compared to wild-type macrophages, with R-LD leads to a remarkable greater amastigote numbers accompanied by elevated IL-10/IL-12 ratio." (PMID 35925884, 2022). "However, once Schistosoma eggs are produced at 5–6 weeks of infection, the host immune status dramatically shifts to a Th2 response, as shown by the increased production of Th2-associated cytokines IL-4, IL-5, IL-10, and IL-13." (PMID 35584107, 2022). "Additionally, many studies involving P. falciparum natural infections endorses the protective role of IL-10 and suggests to further investigate underlying protective mechanisms with different proteins." (PMID 35277125, 2022). "Similar to what was found in the Lm systemic infection model, NK cells are able to produce IL-10 in the early infection phase, but sustained IL-10 production at the late phase of the infection is associated with the increased susceptibility of the host to the systemic infection." (PMID 35053151, 2021). "We measured the levels of IFN-gamma, IL-4, IL-10, IL-17A, IL-23, and IL-9 in the serum samples and PBMCs from the KO and WT mice at different stages of infection to conduct and extensive analysis of how USP21-deficient Tregs affect the resistance of mice to S. japonicum." (PMID 33628844, 2021). "Similarly, in the experimental mice model with L. chagasi infection, IL-10 secretion by B1 B cells precedes host susceptibility while infection with the parasite." (PMID 34209841, 2021). "The increased secretion of IL-10 might influence host cell susceptibility towards infection and masking of an immune response." (PMID 34209841, 2021). "Therefore, microbiota-depleted interleukin-10 deficient (IL-10−/−) mice were perorally infected with C. jejuni and treated with clove EO via drinking water starting on day 2 post-infection." (PMID 33807493, 2021). "Finally, the authors examined STAT3 activation, IL-10 production, Lm burden, and inflammatory myeloid cell accumulation in the organs of IL-10Rα deficient-NK cells (NKIl10R−) mice at 72 h post-infection with Lm." (PMID 35053151, 2021). "In human, HW infection has been associated with an increase in regulatory T cells (Treg), upregulation of regulatory cytokines such as interleukin 10 (IL-10) and transforming growth factor beta (TGFβ), an unbalanced Th1/Th2 response and a higher baseline level of tumor necrosis factor." (PMID 34111180, 2021). "The IL-10-deficient NK cell Ncr1-iCre-Il10fl/fl mouse strain and wt B6 mice were infected with Lm peroral (PO) or coinfected with S. pneumoniae intratracheal (IT) + Lm PO, and the spleens, livers, and lungs were harvested at 3 days post-infection." (PMID 35053151, 2021). "However, in LRTIs, IL-10 shows elevation in moderate and severe cases more than in mild and silent infections and is positively associated with respiratory failure and hypoxemia." (PMID 34578465, 2021). "Interleukin-10, which is classically associated with Treg, was highly upregulated at 14- and 21 dpe, however, it can be produced by numerous different myeloid and lymphoid cells during an infection." (PMID 33621237, 2021). "This contrasts with an excessive secretion of anti-inflammatory cytokines (IL-10), which might lead to the persistent immunoparalysis and high risk of secondary infection." (PMID 34488665, 2021). "When challenged with a lethal dose of H1N1 PR8, the IL-10-deficient mice had reduced mortality but equivalent weight loss and only slightly elevated inflammation when compared their wild type counterparts at days 6-7 post-infection." (PMID 33680987, 2021). "Accordingly, the susceptible phenotype of CBA/J to M. tuberculosis infection is more clearly seen during chronic infection; however, the blockade of IL-10 signaling during the first 21 days of infection was sufficient to revert the susceptible phenotype of CBA/J mice." (PMID 34554927, 2021).